PPARG (peroxisome proliferator activated receptor gamma)
Diseases named in the same sentence as PPARG in open-access papers (continued):
Sharing a sentence is not in itself a finding about the gene and the disease.
liver fibrosis (continued). "Here, we sought to selectively activate PPARγ in liver macrophages with a low dose of the GW1929 agonist linked to dendrimer–graphene nanostars to selectively stimulate a M2 anti-inflammatory macrophage phenotype and to boost macrophage-driven liver fibrosis resolution." (PMID 37242695, 2023). "Moreover, ectopic expression of KLF14 or inhibition of EZH2 with EPZ-6438 treatment could restore PPARγ expression and alleviate fibrosis in a rat thioacetamide liver fibrosis model." (PMID 37476157, 2023). "Therefore, SA-mediated PPARγ activation and M2 macrophage polarization could assist in the amelioration of CCl4-induced hepatic fibrosis." (PMID 37760020, 2023). "Furthermore, miNA-34a and miRNA-34c promoted HSCs activation by targeting PPARγ, implying that members of the miR-34 family may be involved in liver fibrosis via PPARγ pathways." (PMID 37190114, 2023). "Moreover, KLF14 could transactivate PPARγ promoter activity to ameliorate liver fibrosis, of which PPARγ played an important role in regulating cell proliferation and cell senescence." (PMID 37551728, 2023). "Thus, circulating PPARγ DNA could be used as a potential biomarker for stratification of liver fibrosis in nonalcoholic fatty liver disease." (PMID 34572442, 2021). "Our results demonstrated that SCST could target HSP90AA1, PPARG, HSP90AB1, STAT1, etc., further regulating the PPARG signalling pathway that is closely related to liver fibrosis, and the flavonoids and phenylpropanoids of SCST are important ingredients against hepatic fibrosis." (PMID 33510287, 2021). "Thus, KLF14 exerts a critical role in liver fibrogenesis, and targeting the EZH2/KLF14/PPARγ axis might provide a novel approach to liver fibrosis treatment." (PMID 34031939, 2021). "Observing that PPARγ downregulation leads to the promotion of liver fibrosis in NAFLD, we could potentially tie in the additional increase in smaller fat droplets seen in the liver, specifically the increase in the fraction of smaller cells visible, with an increase in miR-27-5p." (PMID 33673073, 2021). "PPARγ expression was downregulated during HSCs activation, and its overexpression significantly recovered LD storage in HSCs, and inhibited activation, proliferation, contraction, adhesion, migration, and induced apoptosis and senescence of HSCs, and therefore attenuating liver fibrosis." (PMID 34031939, 2021). "Moreover, studies have shown that KDM3A could regulate the activation of hepatic stellate cells and liver fibrosis through epigenetic regulation of PPARγ." (PMID 32092824, 2020). "Similarly, in a mouse model of carbon tetrachloride (CCl4)-induced liver fibrosis, miR-130/301 was increased and Pparγ and Lrp8 were correspondingly decreased, accompanied by a positive correlation among collagen crosslinking, miR-130a expression, and YAP nuclear localization." (PMID 26667495, 2015). "In addition, the evaluation of the effect of inherited variability of PPARγ2 on liver damage progression may shed light on the possible long-term effects of treatment with PPARγ agonists on liver fibrosis in NAFLD." (PMID 20825652, 2010). "Furthermore, they also found that SA mitigated CCl4-induced liver fibrosis by inhibiting oxidative stress-mediated hepatic cell death and triggering the polarization of macrophages toward an anti-inflammatory M2 phenotype via activating peroxisome proliferator-activated receptor gamma (PPARγ)." (PMID 40406412, 2025). "At the 7.5 mg/kg dose, NIC significantly enhanced the expression of SIRT-1, AMPK, PGC1-α, PPARγ, and STAT3 by 2.43-, 2.56-, 3.14-, 1.76-, and 1.90-fold, respectively, compared to the TAA-induced liver fibrosis group, and reduced HIF-1α expression by 28.23%." (PMID 41365955, 2025). "Our findings suggest that TNF, IL-6, PPARG, and MMP9 are potential therapeutic targets that influence liver fibrosis progression by regulating inflammatory responses and apoptosis through multiple pathways." (PMID 39869574, 2025).
liver fibrosis (continued). "Among the top 15 TFs, three TFs were closely related to the pathology of NASH and liver fibrosis, i.e., STAT3, NFκB, and PPARγ." (PMID 39338294, 2024). "We previously reported that one selective PPARγ modulator, SR1664, reduced toxin-induced hepatic fibrosis and the activation of hepatic stellate cells (HSCs), the main collagen-producing liver cell in fibrosis." (PMID 37886997, 2023). "In conclusion, the selective activation of PPARγ in hepatic macrophages with DGNS-GW significantly reduced hepatic inflammation and stimulated extracellular matrix remodeling in experimental liver fibrosis." (PMID 37242695, 2023). "We wondered whether the selective activation of PPARγ in liver macrophages with a low dose (1/4 of conventional dose) of GW1929 that was linked to DGNS could be effective in stimulating a selective M2 anti-inflammatory macrophage phenotype and boosting macrophage-driven liver fibrosis resolution." (PMID 37242695, 2023). "The repression of PPARγ by EZH2 can be alleviated in both cardiac and liver fibrosis through the overexpression of miR-214 and miR-29a, respectively." (PMID 37476157, 2023). "Natural and synthetic PPARγ agonists have shown potential in the treatment of various liver diseases, including non‐alcoholic fatty liver disease (NAFLD), autoimmune hepatitis, liver fibrosis and hepatocellular carcinoma." (PMID 33438347, 2021). "PPARG plays an important role in the inhibition of HSC activation and has been proposed as a potential molecular target for liver fibrosis." (PMID 34301291, 2021). "The key targets included 8 co-targets, including HSP90AA1, PPARG, HSP90AB1, STAT1, etc., which play pivotal roles in the pathogenesis of liver fibrosis." (PMID 33510287, 2021). "In conclusion, levo‐tetrahydropalmatine attenuated liver fibrosis by inhibiting ECM deposition and HSCs autophagy via modulation of PPARγ/NF‐κB and TGF‐β1/Smad pathway." (PMID 33438347, 2021). "Meanwhile, TGF-β1 may downregulate the peroxisome proliferator-activated receptor γ (PPARγ) expression through β-catenin dependent Wnt signaling pathway, subsequently contributing to increased collagen-1α1 levels in HSCs, potentially resulting in liver fibrosis." (PMID 31652636, 2019). "Both hBM-MSCs and hBM-MSCs-Ex treatment significantly inhibited the expression of PPARγ, Wnt3a, Wnt10b, β-catenin, WISP1, Cyclin D1, α-SMA, and Collagen I in both HSCs and liver fibrosis tissues (p < 0.005, p < 0.001)." (PMID 30885249, 2019). "The researchers concluded that PPARγ, induced by rosiglitazone, blocks the activation of HSCs and eliminates the expression of TGF-β1 and CTGF, thus improving liver fibrosis." (PMID 26941644, 2016). "Accordingly, the present study has been focused on investigating the potential effect of a drug with combined effects such as TELM, an AT1 receptor blocker and a PPARγ activator, either alone or combined with PZQ, on S. mansoni-induced liver fibrosis in mice." (PMID 23829789, 2013). "The present study has aimed at testing the anti-fibrogenic effects of telmisartan; an AT1 receptor blocker and a PPARγ partial agonist, alone or combined with praziquantel (PZQ) on Schistosoma mansoni-induced liver fibrosis in mice." (PMID 23829789, 2013). "Whether PPARγ, HIF-1, STAT3, or other unrevealed transcription factors are involved in the induction of GPR81 in liver fibrosis is worthy of further investigation." (PMID 38982366, 2024). "Since STAT3, NFκB, and PPARγ are closely related to the pathology of NASH and liver fibrosis, we hypothesized that XYS may exert antifibrotic effects through these three TFs." (PMID 39338294, 2024). "By combining transcriptome analysis with network pharmacology analysis, we demonstrated that the therapeutic mechanism of XYS in NASH-related liver fibrosis involves the regulation of STAT3, NFκB, and PPARγ and their downstream genes and the intervention of the ECM, inflammation, and metabolism." (PMID 39338294, 2024).
liver fibrosis (continued). "The modulation of PPARγ has been proven to attenuate HSC activation and to reduce liver fibrosis." (PMID 37242695, 2023). "Moreover, our previous studies have demonstrated that PPARγ activation promotes M2 polarization of hepatic macrophages, thus decreasing NASH-related inflammation, lipid accumulation, and liver fibrosis in mice." (PMID 37760020, 2023). "Emerging evidence suggested that MSCs-Exo could inhibit liver fibrosis by multiple processes, including autophagy, TGF-β/smad, Wnt/β-catenin, LPS/TLR4, EMT/ERK1, PPARγ, NF-κB pathway." (PMID 36698192, 2023). "Several genes are highlighted explicitly in liver fibrosis, such as PTEN and PPARγ." (PMID 36864460, 2023). "Accordingly, these compounds of HQD may prevent the further development of liver fibrosis by alleviating liver inflammation through influencing the expression of PTGS2, PPARD, and PPARG." (PMID 34301291, 2021). "In a CCl4-induced liver damage model, null mice for PPARγ in macrophages and HSC showed aggravated liver necroinflammation and fibrosis compared to Pparγ-DHEP mice and control mice demonstrating the important role of alterations in macrophages and HSCs in liver fibrosis." (PMID 34361064, 2021). "In addition, PPARγ can reduce the overexpression of α-SMA, type I collagen, and hydroxyproline and thereby inhibit liver fibrosis." (PMID 34361064, 2021). "KLF14 exerts a critical anti‐fibrotic role in liver fibrosis, and targeting the EZH2/KLF14/PPARγ axis might be a novel therapeutic strategy for liver fibrosis." (PMID 34031939, 2021). "Importantly, KLF14 expression was decreased in human with liver fibrosis, which was significantly correlated with EZH2 upregulation and PPARγ downregulation." (PMID 34031939, 2021). "Indicating that the inhibition of PPARγ in HSC is responsible for the increased transcription of TIMPs, the overexpression of PPARγ reduces the expression of TIMP1, TIMP2, and alpha smooth muscle actin (αSMA) and reverses hepatic fibrosis." (PMID 32660130, 2020). "SREBP1c elevated PPARγ and MMP1 protein levels in the model of liver fibrosis." (PMID 32678475, 2020). "Peroxisome proliferator activated receptor-γ (PPARγ), a key regulator in HSC activation and phenotypic alteration, was tested after vimentin silence to assess the potential influence of vimentin on liver fibrosis." (PMID 31581522, 2019). "In addition, we found that hBM-MSCs-Ex inhibited the expression of Wnt/β-catenin pathway components (PPARγ, Wnt3a, Wnt10b, β-catenin, WISP1, Cyclin D1), α-SMA, and Collagen I, in both HSCs and liver fibrosis tissue." (PMID 30885249, 2019). "Based on previous research and the present findings, the bifunctional pharmacological activities of telmisartan, as an angiotensin II receptor antagonist and PPARγ partial agonist, significantly ameliorate NAFLD activity, alter hepatic fat accumulation, and improve hepatic fibrosis." (PMID 30850637, 2019). "However, little is known regarding the effect of PPARγ on HSC activation and hepatic fibrosis under hypoxia stress." (PMID 29686697, 2018). "In line, rosiglitazone (Avandia, GlaxoSmithKline) – a thiazolidinedione – could both reduce hepatic fibrosis in mice by downregulation of the protein expression of α-SMA, TGF-β1, and CTGF and re-establish the expression of PPARγ." (PMID 26941644, 2016). "Therefore, targeting key nodes within the macrophage metabolic-signaling network—such as PPARγ/CD36, Foxo1 phosphorylation, mitophagy, and glycolytic enzymes—may offer multi-mechanism therapeutic strategies for liver fibrosis." (PMID 41459510, 2025). "Specifically, MST1 kinase enhances the PPARγ/CD36 pathway to improve phagocytic function, upregulate fibrolytic genes including Arg1 and Mmps, and suppress the NF-κB signaling pathway, ultimately ameliorating schistosome egg-induced granulomas and liver fibrosis." (PMID 41459510, 2025).
liver fibrosis (continued). "Moreover, we predicted that narcissin from BR, casuarictin from PRA, and γ-sitosterol from BR and ZRR, are the active compounds in XYS responsible for its therapeutic effect on NASH-related liver fibrosis, through targeting STAT3, NFκB, and PPARγ, respectively." (PMID 39338294, 2024). "Our previous study showed that SR1664 improved established carbon-tetrachloride-induced hepatic fibrosis, suggesting that the antifibrotic effects of PPARγ may be mediated through its non-adipogenic transcriptional activity." (PMID 37886997, 2023). "While there was no improvement of NASH fibrosis in the FLIRT study, hepatic fibrosis was, nonetheless, improved by rosiglitazone in MCD diet-fed C57BL6/J mice, and this was attributed to activation of PPARγ, which caused reduced HSC activation and suppressed expression of TGF-β1 and CCN2." (PMID 37629004, 2023). "A recent analysis of mouse and human single and bulk RNA-seq data revealed that PPARγ controls the expression of a set of antifibrotic miRNAs, including miR-30, miR-29c, and miR-338, that are important for the maintenance of low profibrotic protein levels during HCC-related liver fibrosis." (PMID 34638914, 2021). "By using PPARγ antagonist GW9662 and specific LV‐shRNA, we found that PPARγ inhibition significantly decreased the inhibitory roles of KLF14 overexpression in HSCs, and in vivo study confirmed that KLF14 overexpression ameliorated TAA‐induced liver fibrosis in PPARγ‐dependent manner." (PMID 34031939, 2021). "Then, they showed that RA and BC suppressed the expression of EZH2 methyltransferase with consequent reduction of PPARγ H3K27di-methylation which resulted in the formation of euchromatin and increased transcription of PPARγ leading to inhibition of HSC activation and progression of liver fibrosis." (PMID 25380300, 2014). "Although STAT1 and HSP90AA1 have no direct targets, SCST indirectly affects PPARG, STAT1 and HSP90AA1 to exert anti-fibrosis effects through XDH, which is also closely related to liver fibrosis." (PMID 33510287, 2021). "PPARγ agonist ameliorates LSECs activation and inflammation; while PPARβ/δ and PPARα agonists induce ICAM-1 expression in non-stimulated ECs playing an important role in liver fibrosis." (PMID 34361064, 2021). "Next, we investigated whether KLF14 regulated hepatic fibrogenesis in vivo, we ectopically enforced the KLF14 expression in a TAA‐induced rat liver fibrosis model by injecting KLF14‐expressing adenovirus via tail vein, with or without PPARγ inhibition by intraperitoneal GW9662 administration." (PMID 34031939, 2021).
lung carcinoma (160 papers, 2005 to 2026). "PPARγ activating drugs are associated with a lower risk of developing lung cancer and have been shown to prevent smoke-induced lung cancer in mice." (PMID 40303399, 2025). "Although TZDs were developed as an anti-diabetic drug and known to cause side effects, the potent PPARγ activating effects of TZDs have driven extensive exploration of their potential as anti-cancer therapies for lung cancer." (PMID 38397426, 2024). "For instance, Src inhibition has been linked to the induction of FABP4-mediated lipolysis via PPARγ activation, which contributes to the inhibition of lung cancer growth." (PMID 38921583, 2024). "Loss of FZD9 in these cell lines altered expression of lung cancer associated genes and targets of PPARγ, a downstream measure of FZD9 activity." (PMID 35924166, 2022). "Tro significantly upregulated PPARγ and caused apoptosis in NCI-H23 lung cancer cells via a mitochondrial mechanism that was PPARγ- and ERK1/2-dependent." (PMID 35631448, 2022). "PPARγ has been found to be essential to CBD-induced apoptosis in lung cancer in vitro, and it has also been implicated in upregulating autophagy." (PMID 35740979, 2022). "Recently, peroxisome proliferator-activated receptor gamma (PPARγ) agonist drugs such as rosiglitazone sensitize PTEN-deficient resistant human lung cancer cells to EGFR tyrosine kinase inhibitors by inducing autophagy." (PMID 30445769, 2018). "In this study, we explored how PPARγ regulates lipid metabolism and what is the underlying biochemical mechanism for its anti-proliferative function in lung cancer." (PMID 29137280, 2017). "Lastly, we showed that tumor suppressive function of PPARγ is clearly associated with regulating intracellular REDOX balance in lung cancer." (PMID 29137280, 2017). "Manifold molecular mechanisms underlie the antitumor effects of PPARγ and its activation in lung cancer." (PMID 27698657, 2016). "An ongoing trial at the Denver Veterans Affairs Medical Center is evaluating the effect of the PPARγ agonist, pioglitazone, on lung cancer incidence in high-risk current and former smokers." (PMID 24840047, 2014). "Genetic variants in the PPARγ gene have also been identified that are associated with a decreased risk for lung cancer." (PMID 22934105, 2012). "PPARγ deficiency is also linked to pulmonary disorders such as asthma, lung cancer, cystic fibrosis, and inflammation, and PPARγ has been suggested to be a potential therapeutic target to treat these diseases." (PMID 21664456, 2011). "Recently, however, PPARγ has also been implicated in regulating multiple types of cancer, including lung cancer." (PMID 22145026, 2011). "Clinically, use of thiazolidinediones, which are pharmacological activators of PPARγ is associated with a lower risk of developing lung cancer." (PMID 22145026, 2011). "Genetic variants in the PPARγ gene have been identified which are associated with a decreasedrisk for lung cancer." (PMID 18509496, 2008). "Nevertheless,activation of PPARγ is strongly associated with decreased lung carcinoma cell proliferation bothin vitro and in vivo." (PMID 18704200, 2008). "Arsenic exposure increases lung cancer risk, yet its molecular mechanisms remain unclear but are linked to peroxisome proliferator-activated receptor gamma (PPARγ)." (PMID 42041527, 2026). "Moreover, another study on human NSCLC cell lines, HCC827 and H1650, demonstrated that PPARγ agonists sensitize PTEN-deficient lung cancer cells to EGFR TKIs via autophagy induction." (PMID 37190124, 2023). "Because active PPARγ can decrease iNOS expression, and iNOS production is linked to inflammatory and environmental variables that increase lung cancer risk, this difference in the expression pattern could be attributed to NSCLC etiology." (PMID 35631448, 2022). "PPARG is expressed to different degrees in adipose tissues, liver, skeletal muscle, kidney, pancreas and other tissues, and is also one of the pathogenic targets of lung cancer." (PMID 36339610, 2022).